IL1B (interleukin 1 beta)
Diseases named in the same sentence as IL1B in open-access papers (continued):
Sharing a sentence is not in itself a finding about the gene and the disease.
infection (continued). "It thus is possible that the role of IL-1β is dependent on the spatial and temporal context during the infection with Mtb." (PMID 34324582, 2021). "Forty-eight hours post-infection, culture supernatant was collected and bioactive IL-1β was measured as in (B)." (PMID 33410748, 2021). "Specifically, IL-6, IL-1RA and IL-1β were decreased during infection in both therapeutic and preventive groups." (PMID 34112954, 2021). "The levels of interleukin 8 (IL-8) and IL-1β were also significantly higher in milk of cows challenged with MOK124 compared to cows challenged with MOK023 during the first week of infection." (PMID 34740333, 2021). "IL-1β is a polypeptide that is produced by macrophages, fibroblasts, and neutrophils in response to invasive effects such as infection or injury." (PMID 33925737, 2021). "In epithelial cell models, the production of IL-1β showed only a minor peak at the basolateral membrane, after 72 h of infection." (PMID 34578465, 2021). "Bt infected ASC and CASP1 KO cells produced significantly lower amounts of IL-1β as compared to wildtype cells, confirming that pyroptosis and its downstream signalling pathways were activated during Bt infection." (PMID 34821529, 2021). "It has been reported that the infection with SARS-CoV-2 can cause a cytokine storm in patients with symptoms severe or critical, consisting of an increase of IL-1β, IL-4, IL-6, IL-10, IL-17, TNF-α, G-CSF, GM-CSF, IFN-γ, CCL2, CXCL8, and CXCL10." (PMID 33917837, 2021). "Secondly, neglecting their origin, blockade of total IL-1β signaling is bound to heighten the probability of infection." (PMID 34443594, 2021). "Microglia get stimulated due to aging, oxidative stress, air pollution, and infection which causes the production of pro-inflammatory mediators such as NO, TNF-α, IL-1β, iNOS, and COX2." (PMID 34122094, 2021). "Neutrophils are an important source of interleukin (IL)-1β and other cytokines because they are recruited to sites of infection and inflammation in high numbers." (PMID 34010648, 2021). "As we expected, ASFV-Δ7R infection induced higher levels of IL-1β and IFN-β compared with its parental ASFV HLJ/18 strain." (PMID 34310655, 2021). "Respiratory epithelial cells isolated from obese individuals supports higher IAV replication but expresses lower IP-10 and IL-1β in response to infection compared to healthy donor cells in-vitro." (PMID 34959590, 2021). "Compared with the mock infection, pro-IL-1β in cell lysates, IL-1β and cleaved caspase-1 (p20) in supernatants were induced by LPS, LPS/Nigericin, and SFTSV." (PMID 33708197, 2021). "IL-1β neutralization reduced CXCR2 MFI to pre-infection levels on total and CD11bhi blood neutrophils in both QQ and RR mice." (PMID 33718269, 2021). "GTP vaccine strains infection alone can enhanced the mRNA expression of IL-1β, TNF-α, IL-6, IL-10, while the expression of IFN-α mRNA is inhibited." (PMID 33827620, 2021). "The level of IL-1β was markedly increased in culture supernatant upon infection with P. aeruginosa, which was significantly and dose-dependently inhibited by quercetin (% inhibition ranged from 2.96–76.11%)." (PMID 32817626, 2020). "While these studies have shown that inflammasome activation and IL-1β production can control the infection, other authors showed that inflammasome activation can contribute to increased pathology and disease exacerbation." (PMID 31961876, 2020). "LDH and IL-1β levels in supernatants indicated that while infection of macrophages with all strains (125/99, 125/99ΔStx2, or C600) induced IL-1β release, the only one that was associated with a lytic mechanism was 125/99." (PMID 31947665, 2020). "Infection by the low-virulence isolate Nc-Spain1H triggered an increase in the expression of important pro-inflammatory cytokines such as IL-1β, IL-8, IL-12p40, IFN-γ, TNF-α and iNOS as early as 10 dpi (P < 0.1–0.001)." (PMID 32552750, 2020).
infection (continued). "At 24 h post-infection, the mRNA expression of pro-inflammatory cytokines (i.e., Tnf-α, Il-1β, and Il-6) in both the cerebral cortex and hippocampus homogenates was evaluated by RT-PCR." (PMID 32676082, 2020). "ETEC K88 treatment for 6 h till 24 h resulted in the increased levels of IL-1β and IL-8 (P < 0.05 or P < 0.01) whereas 3 h till 24 h infection induced a significant augmentation of TNF-α." (PMID 32774852, 2020). "IL-1α, IL-1β, IL-4, and IL-6 showed infection-specific relative responses, with higher levels in septic TKR than both aseptic TKR and primary TKA (p < 0.05)." (PMID 32708756, 2020). "IL-1α and IL-1β increase acute-phase signalling, trafficking of immune cells to the site of primary infection, epithelial cell activation, and secondary cytokine production." (PMID 32961074, 2020). "A low amount of IL1B production was detected early during whole blood infection with C. albicans (4 h), and blocking of TGF-β1 significantly increased IL1B synthesis." (PMID 32393780, 2020). "Daily treatment with artesunate, started two weeks after the infection, was able to significantly reduce IL-1β, IL-6, and TNF-α levels in paw tissue." (PMID 32230725, 2020). "GEM treatment (100 μM) of BMDMs dramatically suppressed the expression of a variety of inflammatory cytokines and chemokines (Il6, Il12p40, Il1b, Cxcl10, and Cxcl5) at 18 h after infection." (PMID 32155958, 2020). "Activation of these cells following infection appears to elicit similar antiviral responses to both viruses, which consist of increased levels of IL-1β (due to maturation of caspase 1), IFN-β, and other pro-inflammatory cytokines and chemokines." (PMID 32850501, 2020). "The production of pro-inflammatory cytokines as IL-1β and IL-18 by monocytes and macrophages at this early interaction will dictate much of the infection evolution." (PMID 31961876, 2020). "S. typhimurim grown to stationary phase, which resulted in the reduced expression of SPI-1, elicited similar amounts of IL-1β released from cultured WT and Arhgef2-/- BMDMs at 16-h post-infection." (PMID 32075101, 2020). "Larvae that had recruitment of macrophages to the site of infection had significant increases for TNFα, interleukin-1-beta (IL1β), and interleukin-6 (IL-6), and this increase in expression in recruited larvae was independent of dissemination." (PMID 32776983, 2020). "IL-1β is a potent pro-inflammatory cytokine that together with TNF-α plays a crucial role in host-defense responses to infection by bacteria, virus, parasites." (PMID 32983178, 2020). "We show here that MEVs carrying mycolactone induce IL-1β secretion, accounting for the inflammatory response observed some distance away from the infection site, as already reported for other mycobacteria." (PMID 33338061, 2020). "Cytokines such as IL-6, IL-1β, IL-17 and TNF-a have been associated with exacerbation of the infection, with TNF-a, an important NO inducer, being particularly significant in mucosal leishmaniasis evolution." (PMID 32321156, 2020). "It is shown that cells treated with Z. morio hemolymph produced significantly less IL-1β and IL-18 as compared to the infected-only group 18 and 24 h post-infection." (PMID 32998225, 2020). "Classic proinflammatory cytokine genes including IL-1β and TNFα play a key role in the regulation of the inflammatory process at the early stages of infection in fish, providing the first line of host defense." (PMID 32260212, 2020). "The host response to infection is compromised in CF; however, abnormally elevated levels of the pro-inflammatory cytokines IL-6, IL-1β, IL-8 and TNFα have also been found in uninfected CF immortalised cell lines and ex vivo lung explants." (PMID 32781694, 2020). "We found that naïve WT BMDMs did not produce measurable levels of pro- (38 kDa) or active (18 kDa) IL-1β, whereas both forms of the cytokine were robustly detected after infection with live N. caninum tachyzoites." (PMID 32523898, 2020).
infection (continued). "The mechanisms of NLRP3 inflammasome activation required for IL-1β generation during infection by Leishmania have been recently elucidated." (PMID 33061823, 2020). "Here, it was demonstrated that animals infected with Salmonella exhibited significantly high levels of IL-1β in the peritoneal cavity, coming from the inflammatory response against the infection." (PMID 33237133, 2020). "In Mtb-infected hMDMs, however, DFX boosted secreted levels of IL1β and TNFα, exhibiting significant effects on IL1β at 0 and 3 h post infection, while displaying a significant effect on TNFα levels when added 24 h before infection." (PMID 32477344, 2020). "In the present study, the expression of Th17-related mRNA showed that IL-23 and IL-6 were significantly activated early during infection, while IL-1β and IL-17 were highly activated after 6 h post infection." (PMID 33520738, 2020). "IL-1β can induce local mucosal immune responses by stimulating T-cell proliferation and can direct neutrophils to the site of injury or infection." (PMID 33143375, 2020). "H. pylori induces the production of several cytokines including IL-1β after infection of humans or mice." (PMID 32230726, 2020). "First, an obvious increase in the levels of IFN-γ, IL-6, IL-1β, IL-1Ra, IL-18, IL-5, IL-8 was detected in the early (3 dpi) stage of infection, indicating the activation of innate immune responses, such as monocytes and NK cells." (PMID 33180882, 2020). "IL-1β defends against infection by rapidly recruiting neutrophils to the infected site, activating endothelial adhesion molecules, driving production of anti-microbial peptides, and the elaboration of other cytokines and chemokines." (PMID 32983094, 2020). "We observed that infection led to increased expression, particularly of IFNα, IFNγ, IL1β, and IL6 on day 1 post‐challenge." (PMID 32319216, 2020). "While IL-1β can induce CMV reactivation from latency in cell culture and in mouse models, evidence also suggests that CMV employs several mechanisms to counter IL-1β activity—potentially limiting its antiviral effects to allow for more robust infection." (PMID 33089035, 2020). "At 1 day post infection, we observed significantly increased release of IL-1β in cells either exposed to HIV-1 or HIV+Meth." (PMID 32117283, 2020). "Here, we showed that anti-IL-1β neutralizing antibody treatment decreased body temperature and mortality following infection with virulent NDV." (PMID 32293543, 2020). "IL-1β is related to the resistance of the host to infection through stimulation of the IL-1 receptor and activation of the adapter protein MyD88, leading to the production of NO in macrophages." (PMID 32266161, 2020). "The recruitment of immune cells to local sites of infection through the upregulation of chemokines and cytokines has been attributed to the activating effect of IL-1β during infection." (PMID 32973778, 2020). "Together, these results indicated that the K+ efflux, ATP receptor P2X7, and production of reactive oxygen species (ROS) were all involved in IL-1β secretion during the SS2 infection." (PMID 32922370, 2020). "Of note, however, IFNβ represents an immediate early response of infected cells, and plays a major role during the initial phase of infection, likely before IL1β-producing cells are recruited to and become activated at the site of infection." (PMID 33002089, 2020). "According to our settings, such the potent inhibitory activity of quercetin was clearly demonstrated through its ability to efficiently inhibit IL-1β during P. aeruginosa infection, pre- or even post-infection." (PMID 32817626, 2020). "It had been reported that the expression of inflammatory cytokine genes like TNFα, IL-1β, IL-6 and IL-8 were up-regulated by the infection of Ich in rainbow trout larvae." (PMID 32295151, 2020). "We observed that IL-1β secretion was almost completely abolished in the Asc−/− BMDCs compared to the wild-type BMDCs upon infection by WT C. neoformans (panel a versus panel b)." (PMID 32398313, 2020).
infection (continued). "Infection of P. zopfii GT-II induced pro-inflammatory responses in bMECs as demonstrated by upregulated mRNA expression of IL-1β, TNF-α and IL-8 (after 2 hpi)." (PMID 31959834, 2020). "Recombinant active IL-1β and adoptive transfer of IL-1β-expressing neutrophils helped control infection and enhanced bacterial clearance." (PMID 32917040, 2020). "As DFX induced the highest levels of IL1β 3 h post infection, we selected this time point for subsequent experimental analyses." (PMID 32477344, 2020). "We show that C. albicans strain P78042, which does not form robust hyphae and only triggers glucose starvation-dependent inflammasome activation in macrophages, can nevertheless induce production of IL-1β in the murine infection model." (PMID 32750090, 2020). "H. pylori/Nigericin-treated cells also exhibited a similar decrease in mature IL-1β secretion at later periods of infection due to both decreased NLRP3 expression and inflammasome activation." (PMID 32230726, 2020). "IL-1β produced in the epidermis enhances infection and recruitment of myeloid cells to the site of infection, while neutralizing antibodies against IL-1β show a reduction in the infection on LC, dermal DCs, and macrophages." (PMID 33193307, 2020). "While expression of IL-17A and IL-1β was highest early after infection, expression of IL-23 was elevated in the late stage of HN878 infection when differences in susceptibility between the sexes became apparent." (PMID 32198367, 2020). "In the later stages of infection, caspase-1, and inflammasome would become more important for the production of mature IL-1β." (PMID 33644037, 2020). "vICA restrains death-associated inflammatory signaling in myeloid cells such that ∆M36 infection exhibited elevated levels of TNF production or processing of inflammatory cytokine IL-1β when compared to K181." (PMID 33126536, 2020). "On day 5 post-infection, both oral administration of valine and intraperitoneal injection of CoA can significantly reduce virus titers and levels of IL-1β, IL-6, and IL-10 of the lungs and at the same time upregulate IFN-β and IFN-γ of the lungs." (PMID 32345342, 2020). "pylori-infected primary M1 and M2 cells secreted IL-1β, which gradually increased between 6 h to 24 h of infection." (PMID 32230726, 2020). "The optimal stimulation conditions for SS2 to induce IL-1β production was 16 h post infection and a MOI of 1 with peaked IL-1β production (2,200 ± 605 pg/ml) without too much cytotoxicity (20.2 ± 4.6%)." (PMID 32922370, 2020). "The mRNA levels of Tnf, Il6, and Il1b were significantly increased in BMDMs from Ppara-/- mice, compared with Ppara+/+ mice, at 6 h after Mabc infection." (PMID 32155958, 2020). "Non-cytotoxic ILC1s, which are stimulated by the presence of Il-12 and Il-18, confer immunity to infection with intracellular bacteria and protozoa, while Il-1β/Il-23-dependent ILC3s response protects the host from infection with extracellular bacteria." (PMID 33255175, 2020). "It has also been observed in human skin explants infected with DENV-2 that the IL-1β produced in the epidermis promotes the infection, recruitment, and migration of myeloid cells." (PMID 33193307, 2020). "Infection with P. zopfii GT-II in MEC induced early IL-1β, TNF-α and Cxcl-1 gene expression (after 2 hpi)." (PMID 31959834, 2020). "In contrast, later stages of infection are likely to be affected by the synergy between IFNα and IL1β, as indicated by the enhanced antiviral state inferred from the increased inhibition of LCMV replication in the mouse model." (PMID 33002089, 2020). "The cell-free supernatants after post-infection were analysed for the expression of pro-inflammatory cytokines IL-1β, IL-6 and TNF-α and anti-inflammatory cytokines IL-10, IL-12p40, IL-12p70 and IL-4." (PMID 32295519, 2020). "Infection of human whole blood with any Candida species led to the release of IL-8 and proinflammatory cytokines (IL-1β, IL-6, TNF-α)." (PMID 33024045, 2020).
infection (continued). "T-helper 17 cells play a vital role during bacterial infection by releasing IL-1β and IL-6; it activates and recruits neutrophils to the site of infection." (PMID 33634060, 2020). "Infection with the intestinal helminth Heligmosomoides polygyrus bakeri promotes the local release of IL-1β, leading to diminished production of IL-25 and IL-33, suboptimal TH2 responses and chronic infection." (PMID 33584721, 2020). "In the present study, the effect of IL-1β during infection with virulent NDV was investigated utilizing IL-1β-specific neutralizing antibodies." (PMID 32293543, 2020). "DFX also supports innate immune function by inducing IL1β production in human macrophages during early infection with Mtb and upon stimulation with LPS." (PMID 32477344, 2020). "The supernatants from the infected cultures were collected 24 h post-infection and the amounts of IL-12p40, IL-1β, IFN-β, and IL-10 quantified." (PMID 32327653, 2020). "In the present study, we found that secretion and expression levels of IL-1β, IL-8, and tumour necrosis factor-α were increased upon infection with P. gulae." (PMID 32080231, 2020). "During infection, microglial cells are a major source of inflammatory cytokines, including IL-1β, IL-6-α, and TNF-α." (PMID 33251159, 2020). "Conversely, mice infected with IC-deficient rSARS-CoV E exhibit reduced levels of inflammasome-activated IL-1β, and mice recovered from the infection." (PMID 33013759, 2020). "Both types of H. pylori induced the profound expression of pro-IL-1β in THP1 monocytes at 6 h of infection compared to mock-treated control cells." (PMID 32230726, 2020). "Seven cytokines showed an increase in concentration that was dependent on the presence of localized infection: IL-1α, IL-1β, IL-6, IL-8, MCP-1, MIP-1α, and MIP-1β (p < 0.05)." (PMID 32867801, 2020). "To address the physiological relevance of these findings, we measured cell death and IL-1β release in primary human monocytes and macrophages following 24-h infection with Mtb-BFP." (PMID 32385301, 2020). "IL-1α and IL-1β are effectors and amplifiers of responses to various challenges such as infections or tissue injury." (PMID 32733464, 2020). "Following infection with Escherichia coli, cytokine expression of IL-1β, IL-6, TNF-α, and IL-10 in the intestinal mucosa significantly increases, resulting in piglets having greater villous atrophy and intestinal morphology disruption." (PMID 32547405, 2020). "There was a statistically significant difference noted in TNF-α, IL-1β and IL-6 mRNA expression at day 3 and day 7 compared to day 1 post-infection." (PMID 32391391, 2020). "They showed that conventional DC-derived IL-1β preserves and expands IL-1R1hi IL-22+AhR+ immature NK cells, potentially influencing mucosal innate immunity during infection." (PMID 32647342, 2020). "Activated neutrophils produced neutrophil chemokine CXCL2 and expressed TNF-α and IL-1α in addition to very high levels of pro-IL-1β, and these proinflammatory neutrophils were major correlates of lethal infection." (PMID 33062077, 2020). "Allogeneic DCs that are matured ex vivo with a cocktail containing poly(I:C), R848 and IFN-γ in combination with an infection-enhanced adenoviral vector produce high amounts of IL-1β." (PMID 33584721, 2020). "Mice infected with Cr had increased expression of multiple cytokines including IL-17A, IL-22, IL-6, and IL-1β mRNA in colonic tissue 12 days after infection." (PMID 32230738, 2020). "IL-1β, a potent proinflammatory cytokine, is the best-described IL-1 family member that is essential for host defense against infection and injury." (PMID 32423023, 2020). "The NLRP3 inflammasome controls the maturation and secretion of the proinflammatory cytokines IL-1β and IL-18 and is important for the innate immunity against pathogen infection." (PMID 32582195, 2020).